KRAS (KRas proto-oncogene, GTPase)
Diseases named in the same sentence as KRAS in open-access papers (continued):
Sharing a sentence is not in itself a finding about the gene and the disease.
tumor (continued). "KPC-1 tumor-bearing mice injected with anti-KRAS siRNA NP showed decreased tumoral KRAS protein expression as compared to SC-siRNA NP treated mice." (PMID 31413817, 2019). "We next examined the original tumor and MBC02 cell line for the presence of common mutations in KRAS (codons 12, 13, 61, and 146) and BRAF (V600E) that are prevalent among CRC patients." (PMID 30828563, 2019). "Nuclear MEK and YAP staining were increased in tumours with KRAS knockdown or deltarasin treatment, which was also reversed by trametinib." (PMID 30833665, 2019). "KRAS is an operative oncogene that was found to be particularly important in tumor progression and treatment." (PMID 31717759, 2019). "Regardless, oncogenic KRAS has been shown to stimulate a heterocellular signaling with stromal cells, that is essential to fuel tumor cell proliferation." (PMID 31847096, 2019). "Many oncogenes including KRAS are well known to affect the transcriptional machinery, making aberrant translation a widespread characteristic of tumour cells, and the expression of many proteins involved in translation is associated with poor prognosis in CRC." (PMID 31133691, 2019). "CIN occurs more frequently in tumour showing APC and KRAS mutations, whereas the microsatellite instability phenotype is mainly associated with BRAF mutations." (PMID 31414579, 2019). "Circulating tumor DNA (ctDNA) monitoring during therapy can detect emergence of KRAS mutant clones and early resistance to therapy." (PMID 30967998, 2019). "In addition, we examined the clinical sensitivity of Idylla and OncoBEAM plasma KRAS mutation detection at <1% MAF by comparing plasma mutational analysis obtained by both platforms to those obtained by standard-of-care (SOC) FFPE tumor RAS testing on paired primary tumor tissue specimens." (PMID 31222012, 2019). "Either simple linear or multiple linear regression can be run separately stratifying on a patient’s tumor’s KRAS status." (PMID 31174497, 2019). "al., whereby they demonstrate sequential targeting of TGF-β followed by KRAS, which led to tumor uptake and decreased KRAS expression in murine models of PDAC." (PMID 31413817, 2019). "The level of ctDNA (MET amplification and KRAS mutants) correlated with tumor burden and response to therapy." (PMID 31824558, 2019). "The same mutation observed in the tumor was observed in the NTL of 10 patients (21.3%) of the SM group, with similar distribution for EGFR and KRAS mutations (50% of the patients each)." (PMID 30999636, 2019). "Given the contrasting effects of autophagy inhibition on tumor growth in HCT116 and SW480 cells, and given the fact that both are driven by oncogenic KRAS mutations, we next investigated the global cellular processes modulating this opposite cellular response." (PMID 31383875, 2019). "In the context of metastatic CRC, CMS appears to associate with survival in clinical trials of patients with wild-type KRAS tumours, treated with anti-EGFR or VEGF inhibitors." (PMID 31775679, 2019). "Sixteen of 25 plasma samples had detectable level of KRAS (n = 14), BRAF (n = 1) or NRAS (n = 1) mutations, which were 100% concordant to reported tumour DNA genotype." (PMID 30585255, 2019). "Another group employed in silico docking screens to identify a compound, 3144, that inhibits RAS-RAF interactions with impressive in vitro and in vivo activity in KRAS mutant tumor models." (PMID 31878223, 2019). "KRAS can also promote tumour metastasis and EMT progression by inhibiting RKIP in conjunction with MAPK-ERK signalling." (PMID 31684910, 2019). "We also tested the in vivo effects on tumor growth of FASN∆/∆ MEFs infected with KRAS or HER2, grafting them into wild-type animals compared with FASNlox/lox counterparts." (PMID 31676791, 2019).
tumor (continued). "Coming back to our example of the KRAS-driven lung tumor, the computations involved in figuring out what drives a tumor from the exome sequencing NGS reads poses a significant computational challenge." (PMID 31622330, 2019). "The role of KRAS in the modulation of the tumor microenvironment has been demonstrated not only for the immune component but also the stromal one." (PMID 31405063, 2019). "Drug resistance and tumor heterogeneity are formidable challenges in cancer medicine, which is particularly relevant for KRAS-mutant cancers, the epitome of malignant tumors recalcitrant to targeted therapy efforts and first-line chemotherapy." (PMID 31431614, 2019). "We previously reported activating mutations of KRAS, as well as amplification of FGFR2, in a tumor that exhibited extreme resistance to photon radiotherapy." (PMID 31540114, 2019). "Our extensive analysis of miRNAs expression profile performed in tumor samples of CRC patients, has primarily detected an overexpression of miR-425-5p in KRAS-mutated CRC compared to KRAS-wild type CRC and NCT." (PMID 31673240, 2019). "Having established the unique nature of the bronchiolar-induced immune microenvironment in KEAP1-mutant KRAS-driven LUAD, we sought to identify the underlying mechanisms of tumor progression in this genetic subtype." (PMID 31519898, 2019). "For example, miRNAs correlate with microsatellite instability (MSI) status, tumor location, BRAF and KRAS mutation and tumor stage." (PMID 30786859, 2019). "In order to assess the anti-tumor effects of dual anti-miR-21 and si-KRAS therapy in PDAC, we treated cells using either TPN-21, TPN-KRAS, or a combination of both and we compared that to TPN-NT (scramble RNA) or double TPN-NT (combo-NT)." (PMID 31523393, 2019). "Systemic let-7 or miR-34a delivery by injection of neutral lipid emulsion also significantly attenuates tumor burden in the KRAS autochthonous NSCLC mouse model." (PMID 30813457, 2019). "Studies in mice and cell lines have demonstrated that ARID1A is a tumor suppressor that represses KRAS-induced precancerous lesion formation and suppresses ductal proliferation." (PMID 31769422, 2019). "We measured the fractal dimensions (FD) and lacunarity (LC) of Tregs in MT and WT KRAS NSCLC tumor specimens to discern their enrichment." (PMID 31635338, 2019). "These splenocytes were incubated with KRAS* tumor lysate in the presence of murine bone marrow-derived DCs." (PMID 30796212, 2019). "Two patients displayed different mutations with respect to the primary tumor, and in two out of the four patients with a wild type primary tumor, new mutations were highlighted: EGFR p.746_750del and KRAS p.G12V." (PMID 30110953, 2018). "Here we have demonstrated a case where the primary tumor was KRAS mutant but was wildtype in the metastatic sample following chemotherapy." (PMID 29423054, 2018). "The importance of PP2A in EGFR signaling is also illustrated by the finding that administering SMAPs, small molecule activators of PP2A, results in substantial inhibition of KRAS-driven tumor growth." (PMID 29455644, 2018). "Combination of MEK162 plus neratinib inhibits tumor growth in KRAS-mutant inflammatory cell line xenograft." (PMID 30118499, 2018). "KRAS assessment in tumor tissues showed 29 patients with the mutant-type (MT) and 56 patients with the wild-type (WT)." (PMID 29849949, 2018). "This classification takes into account different molecular signatures of the primary tumor, such as MSI, hypermutator status, BRAF and KRAS mutations, WNT and MYC activation, TGF-β activation, and methylation status." (PMID 30282914, 2018). "Later, numerous other studies revealed that, despite the frequently high degree of concordance between alterations in different tumor areas, analysis of a single tumor block led to the incorrect assignment of KRAS and BRAF status in 10–30% of cases." (PMID 30477151, 2018).
tumor (continued). "In conclusion, based on our experience we suggest considering LB for patients who have not had TB or have insufficient tissue to determine the presence of KRAS/NRAS/BRAF mutations, especially in the context of high tumor burden prior to therapy." (PMID 30705875, 2018). "The concordance between ctDNA in urine and mutant KRAS in the tumor was 89% (sensitivity 80%, specificity 100%)." (PMID 30373199, 2018). "Although cell-autonomous pro-tumorigenic functions of mutant KRAS are well charted, mechanisms utilized by the oncogene to co-opt host cells from the tumor microenvironment in order to favor tumor progression have only recently begun to be elucidated." (PMID 29445180, 2018). "The MAPK pathway is upregulated in KRAS-mutated NSCLC15 and in different types of tumor sorafenib can switch off MAPK signaling through Raf inhibition, as evidenced by reduced pErk levels." (PMID 29343688, 2018). "AFs of concordant point mutations and indels in EGFR, KRAS, and PIK3CA ranged from 0.3 to 52% in tumor tissue DNA and in plasma cfDNA from 0.2 11.6%." (PMID 29441349, 2018). "The MAPK and AKT pathways can be uncontrollably activated by mutant KRAS, leading to promoted cell proliferation, migration and invasion in tumor cells." (PMID 29921293, 2018). "KRAS assessment in tumor tissues identified 29 patients with the mutant-type (MT) and 56 patients with the wild-type (WT)." (PMID 29849949, 2018). "In summary, in our study, BET inhibition by BAY 1238097 showed remarkable efficacy against NSCLC and PDAC in vivo, significantly reducing tumor burden in genetic mouse models of KRAS-driven tumors." (PMID 29721157, 2018). "A potential molecular biomarker for palbociclib response is mutant KRAS status, first suggested through in vitro and in vivo work in tumor cell lines and mice where synthetic lethality was observed following CDK4 inhibition." (PMID 30647837, 2018). "KRAS was the most commonly mutated gene to be identified in both tumor tissue and ctDNA, and we used KRAS to evaluate the concordance of ctDNA with tumor tissue." (PMID 29707525, 2018). "Tumor genotyping is become standard practice for CLM and clinicians often have information on the mutational status of oncogenes, including the KRAS, BRAF, PIK3CA, and NRAS oncogenes." (PMID 29774112, 2018). "In summary, the novel mechanism presented here opens new avenues to therapeutically target mutant KRas-dependent human cancers by suppressing GSK3α/β, leading to β-catenin- and/or c-Myc-dependent tumor abrogation." (PMID 30514931, 2018). "The identification of small molecules selectively inhibiting KRAS mutants has been challenging, yet mutant KRAS has recently been shown to be targeted by tumor-infiltrating lymphocyte (TIL)-derived T cells that confer tumor regression upon adoptive transfer." (PMID 30283732, 2018). "These compounds, used at low micromolar levels, were able to inhibit in vitro growth and tumorigenic ability of mutant KRAS tumor cell lines." (PMID 29534749, 2018). "Oncogenic KRAS induces tumor onset and development by modulating gene expression via different molecular mechanisms." (PMID 29440633, 2018). "YAP is induced in a subset of KRAS-driven PDAC tumours following knockdown of KRAS and supports the growth of these tumours." (PMID 30353028, 2018). "In one study, tumor biopsies derived from patients participating in a trial based on cetuximab plus folinic acid fluorouracile ininotecan (FOLFIRI) in patients with KRAS-WT were analyzed by next generation sequencing." (PMID 29652830, 2018).
tumor (continued). "We chose heterogeneous endoribonuclease-prepared siRNA pools (esiRNAs) against the frequently mutated genes PIK3CA and KRAS and coupled them to the anti-EGFR antibody cetuximab, which was internalized specifically into the tumor cells." (PMID 30001368, 2018). "Thirty-one cfDNA samples positive for IDH1, KRAS, PIK3CA, NRAS, AKT, BRAF, and IDH2 mutations in tumor tissue were selected for ddPCR, MassARRAY and NGS comparison." (PMID 29535804, 2018). "For instance, the potential neoantigen based on BRAF V600E mutation and HLA-A03:01 exists in 117 tumor samples, and corresponding neoantigens based on several mutations of KRAS and PIK3CA are also shared in more than 40 tumor samples." (PMID 30223042, 2018). "Only the KRAS G12D and RNF43 G659Vfs*41 mutations were retained from the pre-treatment tumor in the treatment-resistant tumor." (PMID 30458888, 2018). "The prevalence of KRAS and SMAD4 mutations in the Control cell lines was 50% and 17%, respectively, whereas that in cancer type– and sample size–matched clinical tumor populations was 48% and 2.5%, respectively." (PMID 30220971, 2018). "This approach allowed to identify the histone demethylase, whose expression is down-regulated in NSCLC, as a tumor suppressor in the KRAS-driven mouse model: in fact, UTX knockout promotes lung tumor progression in KRASG12D/+ mouse model." (PMID 30060526, 2018). "KRAS mutations undermine EGFR-targeted therapies and variant KRAS-mutant tumor cells contribute to the outgrowth of EGFR-resistant tumor cell populations." (PMID 30283732, 2018). "The study showed that there was a significantly increased overall survival in those patients with WT KRAS tumor status when compared to those with mutant KRAS (9.5 mos vs. 4.8 mos; p=0.041)." (PMID 30197760, 2018). "In summary, our findings revealed a seven-lncRNA signature that predicted OS of NSCLC patients, especially in those with early tumor stage and carrying wild-type KRAS or EGFR." (PMID 30205363, 2018). "miR-143 has been characterized as a tumor-suppressive factor by targeting several oncogenes, including Kirsten rat sarcoma viral oncogene homolog (KRAS) and extracellular signal-regulated kinases 5 (ERK5)." (PMID 30029522, 2018). "Since it became apparent that KRAS mutations are not only prognostic but also predictive of response to anti-EGFR therapy, numerous studies have investigated intra- and inter-tumor heterogeneity for KRAS status." (PMID 30234115, 2018). "In agreement with our findings on the LUAD caused by the EGFR tumor‐driving mutation, HCI‐2509 treatment of C57BL/6N(KRAS G12V) mice resulted a significant increase of H3K4me2 levels, whereas H3K9me2 levels were unaffected." (PMID 30220105, 2018). "Inhibiting or depleting G9a upregulates genes associated with mutant KRAS and extracellular matrix (ECM) regulation, and depleting these genes or overexpressing G9a impedes tumor transplantation." (PMID 30455465, 2018). "Differences in terms of age, primary tumor site, primary tumor resection, performance status, KRAS and RAS status were identified across patients enrolled in the trials." (PMID 29522543, 2018). "We tested the ability of one of our recombinant CDCP1 antibodies to selectively deliver a cytotoxic payload to mutant KRAS tumor cells." (PMID 29359686, 2018). "According to the KRAS detection, the ctDNA had a sensitivity of 66.67% (4/6), specificity of 87.50% (14/16), and concordance of 81.82% (18/20) compared with tumor tissue." (PMID 29707525, 2018). "In a human tumor growth model, the growth of KRAS mutant xenograft tumors was suppressed significantly by the GSC treatment." (PMID 30577618, 2018).
tumor (continued). "We apply the method to ARS-1620, the first covalent KRASG12C inhibitor shown to engage and inhibit KRAS in vivo, inducing tumor regressions in a wide range of KRASG12C cell and patient derived xenograft models." (PMID 30254226, 2018). "In vitro and in vivo functional studies revealed that RASAL2 promoted tumor progression in both KRAS/NRAS mutant and wild-type CRC cells." (PMID 30037330, 2018). "The refametinib/4‐IPP combination significantly induced regression of tumor growth of KRAS mutant CRCs, while the MEK inhibitor or MIF alone with small molecules did not influence tumor growth." (PMID 29896883, 2018). "In the current study, we did not observe marked nuclear localization of YB-1 after irradiation or EGF treatment, or following overexpression of KRAS(G12V) in tumor cells of different origins." (PMID 30126195, 2018). "MiR-216b was first discovered to function as a tumor suppressor involving in regulating nasopharyngeal cell proliferation and invasion as well as tumor growth via inhibiting the KRAS/AKT and ERK pathways." (PMID 30406146, 2018). "Two studies sought to detect emerging resistance to anti-EGFR therapy using sequential analysis of circulating tumor DNA for KRAS status." (PMID 30234115, 2018). "YAP and TAZ, the major downstream targets of the Hippo tumor suppressor pathway, are also regulated by a multitude of other inputs, including KRAS." (PMID 29682330, 2018). "Although GATA2 itself is not druggable, the combined proteasome and Rho signaling inhibition resulted in a robust suppression of KRAS-mutant tumor growth." (PMID 30060526, 2018). "Next generation sequencing found only the KRAS G12D and RNF43 G659Vfs*41 mutations were retained from the pre-treatment tumor in the treatment-resistant tumor." (PMID 30458888, 2018). "Tailoring existing therapies based on tumor sidedness, KRAS, MSI, or BRAF status as well as individualizing treatments for elderly or DM patients represent our current efforts to provide more personalized care in oncology." (PMID 30519549, 2018). "BRAF mutation was detected in the ctDNA of 1 out of 3 patients with BRAF mutant tumours and in 1 additional patient with a KRAS mutant/BRAF wild-type tumour." (PMID 29362371, 2018). "The best prognostic profile in this study was represented by left sided, KRAS wild-type, lung-limited tumor." (PMID 30443292, 2018). "Oncogenic KRAS mutations have been shown to increase regional DNA methylation due to increased SAM obtained via one-carbon metabolism, resulting in increased tumor growth." (PMID 30159313, 2018). "Most patients (94%) had their tumor molecularly genotyped, and abnormalities (e.g., mutations, fusions, and rearrangements) in BRAF, KRAS, and MEK were documented." (PMID 29603015, 2018). "We classified tumours into five different subtypes based on BRAF and KRAS mutation, CIMP status, and MSI." (PMID 30188916, 2018). "KRAS-RalB-NF-κB pathway was both necessary and sufficient for tumor initiation, anchorage independence, self-renewal, and erlotinib resistance." (PMID 30619741, 2018). "Subsequently, we investigated if the elevation of circulating osteopontin in CRLM patients is associated with specific disease characteristics (tumour grading, right- vs. left-sided primary CRC, KRAS mutated patients, patients with different ECOG PS)." (PMID 30373147, 2018).